NLRP3 (NLR family pyrin domain containing 3)
Diseases named in the same sentence as NLRP3 in open-access papers (continued):
Sharing a sentence is not in itself a finding about the gene and the disease.
cancer (continued). "Reactivation of NLRP3 inflammasome could recover impaired cancer cell migration and invasion abilities caused by SOAT1 knockdown." (PMID 40135589, 2025). "In addition to inherited autoinflammatory diseases, dysregulated NLRP3 activation is associated with various human diseases characterized by chronic inflammation, degeneration, and cancer." (PMID 40307577, 2025). "Additionally, the expression of NLRP3 inflammasome components is upregulated in cancer tissue and closely associated with the prognosis of surgically resectable pancreatic adenocarcinoma." (PMID 39969214, 2025). "NLRP3 inflammasome activation has been associated with promoting breast tumor growth, progression, and aggressiveness, as well as with the pyroptotic death of cancer cells." (PMID 39769450, 2024). "NLRP3 has been directly implicated in the pathogenesis of various inflammatory diseases and exhibits a dual function in the development of metabolic disorders and cancer." (PMID 39201564, 2024). "Activation of NLRP3 has been linked to a variety of diseases, from cancer to infectious disorders." (PMID 39062016, 2024). "However, while chronic inflammation caused by NLRP3 inflammasome promotes the occurrence and development of cancer, there is also evidence that these inflammatory factors can induce cell cycle arrest by promoting cell senescence to inhibition." (PMID 38317229, 2024). "Moreover, NLRP3 has been implicated in promoting the proliferation and migration of esophageal squamous-cell carcinoma, suggesting its involvement in cancer progression." (PMID 39769450, 2024). "According to research, NLRP3 inflammasome pathway dysfunction is linked to a variety of inflammation-induced diseases, and genetic variation in the NLRP3 inflammasome pathway gene is linked to the development of malignant tumors." (PMID 37715239, 2023). "Different cancer diseases have been linked to NLRP3 and its role in tumorigenesis may be the opposite." (PMID 37300757, 2023). "However, there have only been a limited number of studies examining the association between mutations in the NLRP3 gene and cancer incidence." (PMID 37885032, 2023). "This could be one of the molecular mechanisms underlying the impact of NLRP3 depletion on macrophages and its effect on cancer biology, as observed in this study." (PMID 37077909, 2023). "NLRP3 inflammasome pathway is closely associated with the occurrence and development of various kinds of cancers and is also considered an important target for overcoming cancer." (PMID 38031068, 2023). "However, aberrant NLRP3 inflammasome activation has been implicated in various inflammation-associated diseases, such as diabetes, atherosclerosis, obesity, cancer, and Alzheimer’s disease." (PMID 37651190, 2023). "In addition to the induction of potent inflammatory cytokines, NLRP3 also suppresses NK cell-associated cancer immunity in various lung metastasis models." (PMID 37528154, 2023). "The NLRP3 inflammasome has a double-edged sword effect in cancer which is dependent on many factors such as the expression of its components, the presence of mutations that affect its expression, cancer type, and stages of tumorigenesis." (PMID 36763290, 2023). "Collectively, these results demonstrate a novel effect of ODZ10117 in regulating NLRP3 inflammasome activation both in vitro and in vivo, making it a promising candidate for the treatment of NLRP3-inflammasome-associated immune disorders and cancer." (PMID 37047051, 2023). "In summary, these data indicate that differential expression of NLRP3 pathway genes is associated with survival probability of cancer patients and extend the findings that NLRP3 inflammasome may have pro- and anti-tumorigenic roles." (PMID 36032139, 2022). "However, their chronic activation, particularly of NLRP3, also underlies numerous common inflammatory diseases, ranging from Alzheimer’s disease, atherosclerosis, and diabetes to rheumatoid arthritis (for cancer, please see 3)." (PMID 36293159, 2022).
cancer (continued). "Further evidence from cancers with virus-triggered etiology and inflammasome genetics in susceptibility to cancer development suggests that the NLRP3 inflammasome may have a protective role in virus-associated cancers." (PMID 36466820, 2022). "Polymorphisms and mutations in the NLRP3 gene are also implicated in cancer." (PMID 35754962, 2022). "GL-V9, a small-molecule AMPK activator, could prevent colitis-associated cancer through the induction of mitophagy-mediated NLRP3 inflammasome inhibition or through triggering autophagy-mediated NLRP3 inflammasome degradation." (PMID 34457117, 2021). "According to recent reports, NLRP3 inflammasome is influenced by molecular patterns which caused by an imbalance of cytoplasmic homeostasis, thus that might be related to cancer development." (PMID 34502191, 2021). "NLRP3 inflammasome plays an important role in the innate immune response, but emerging evidence has indicated that the NLRP3 inflammasome is implicated in all stages of cancer development." (PMID 34502191, 2021). "Indeed, the common mutations to NLRP3 and its downstream mediators varies across cancer types and tissue location; the data on these mutations contradicts the protective findings of NLRP3′s IL-18-mediated downstream activity." (PMID 32098318, 2020). "As we have shown that KRAS causes NLRP3/IL-1β activation, targeting this axis may also be promising to achieve a therapeutic synergism with other anti-cancer therapies." (PMID 33116132, 2020). "Fewer studies have examined the association of the NLRP3 genotypes with cancer." (PMID 32313131, 2020). "Besides, studies utilizing gene expression profiling have also implicated the upregulation of NLRP3 inflammasome in several cancers." (PMID 32733479, 2020). "Additionally, prolonged Hippo pathway inhibition could potentially increase cancer risk, while complete NLRP3 suppression might enhance susceptibility to secondary bacterial infections." (PMID 40659620, 2025). "In Alzheimer’s models, OC-rich diets reduced NLRP3 protein expression by 41% in murine brains, correlating with diminished caspase-1 cleavage (28–45%) and IL-1β levels, demonstrating systemic anti-inflammatory effects translatable to cancer-associated neuroinflammation." (PMID 40564985, 2025). "The NLRP3 inflammasome may contribute to the progression of these cancers by amplifying this risk." (PMID 40718836, 2025). "Additionally, the NLRP3 inflammasome may be closely associated with cancer cell metabolic pathways, particularly the key metabolic processes such as oxidative stress, glycolysis, and fatty acid metabolism." (PMID 40718836, 2025). "Importantly, overexpression of NLRP3 accompanied by hyperglycemia in cancer cells and cardiomyocytes may be associated with the development of subsequent cardiotoxicity." (PMID 38248011, 2024). "When inflammasomes like NLR family pyrin domain containing 3 (NLRP3) are activated, proinflammatory cytokines like interleukin-1 beta (IL-1β) and interleukin-18 (IL-18) are secreted, which can cause a persistent inflammatory state that worsens liver damage and accelerates the growth of cancer." (PMID 38780447, 2024). "Thus, chronic and uncontrolled inflammation caused by NLRP3-dependent and independent mechanisms could lead to many cancer types." (PMID 39769450, 2024). "Similarly, NLRP3 inflammasome genetic variants have been associated to cancer." (PMID 37715239, 2023). "Besides the direct role of aberrant stimulation of the NLRP3 inflammasome, few studies have recently also suggested that the dysregulated interaction between the inflammasome and autophagy can be linked with the development and progression of cancer." (PMID 34684819, 2021). "Among the inflammasomes, NLRP3 is the most well studied and has been associated with the pathogenesis of multiple diseases, including neurodegenerative diseases (Alzheimer’s and Parkinson’s), atherosclerosis, hereditary cryopyrin-associated periodic syndromes (CAPSs), metabolic diseases and cancer." (PMID 34064909, 2021).
cancer (continued). "Similarly, genetic polymorphisms involved with NLRP3 inflammasome have also been linked to cancer." (PMID 32733479, 2020). "Besides NLRP3, a number of NLRs have also been shown to be associated with cancer progression." (PMID 27206676, 2016). "However, whether NLRP3 is important for protection in colitis-associated cancer still remains unclear." (PMID 24273542, 2013). "The NLRP3 inflammasome is a central inflammatory signaling pathway in host defense, cancer, metabolic disorders, and neurodegenerative diseases." (PMID 42162153, 2026). "In contrast, under immune-activated conditions, NLRP3-mediated pyroptosis—particularly through gasdermin D (GSDMD)-dependent pore formation—can induce cancer cell death and enhance antitumor immune responses." (PMID 40718836, 2025). "Among all the inflammasomes, the NLRP3 inflammasome has emerged as a key player in regulating inflammatory responses, particularly within the cancer milieu." (PMID 41376623, 2025). "Taken together, these findings suggest that as the downstream of SOAT1, NLRP3 inflammasome activation positively impacted cancer‐related lymphangiogenesis in OSCC." (PMID 40135589, 2025). "For instance, in CRC, NLRP3 inflammasome activation is associated with epithelial-mesenchymal transition (EMT) and contributes to cancer progression." (PMID 40692785, 2025). "In cancer, autophagy‐related cell death can activate ATP signaling pathways, leading to NLRP3 inflammasome activation." (PMID 40671967, 2025). "Conversely, in certain cancer contexts, curcumin promotes pyroptosis by stabilizing NLRP3 through the inhibition of Smurf2-mediated ubiquitination." (PMID 40806716, 2025). "Multiple earlier studies have reported that the activation of the NLRP3 inflammasome can promote cancer migration and metastasis across various types." (PMID 39858497, 2025). "Across cancers, NLRP3, GSDMD, and SIRT1 emerge as the most recurrent ncRNA-regulated pyroptosis components." (PMID 41291696, 2025). "Targeting NEK7 has emerged as a promising therapeutic approach for diseases involving NEK7 dysfunction, such as NLRP3-related diseases and cancers." (PMID 40076620, 2025). "Repeated treatment with MCC950 attenuated cancer-induced bone-pain-related mechanical allodynia by reversing NLRP3 inflammasome up-regulation in the spinal cord." (PMID 40002330, 2025). "At the same time, curcumin has been shown to enhance pyroptotic cell death in cancer by stabilizing NLRP3 via inhibition of Smurf2, thereby activating the inflammasome complex." (PMID 40806716, 2025). "(2021) identified altered expression of NLRP3 inflammasome-related genes in 15 out of 24 cancer types studied." (PMID 40692785, 2025). "In particular, CASP8 and NLRP3 were hypomethylated in many cancers, whereas RIPK3 was hypermethylated." (PMID 38436818, 2025). "Firstly, although we have explored the cancer-promoting role of NLRP3 in CRC and its potential molecular mechanisms at cellular and animal study levels, our analysis predominantly depends on limited bioinformatics methodologies." (PMID 39744485, 2025). "The mechanistic convergence of NF-κB and NLRP3 inhibition by statins also provides a molecular rationale for their pleiotropic effects beyond cardiovascular protection, including neuroprotection, cancer prevention, and metabolic disease management." (PMID 40943351, 2025). "The activation of the NLRP3 inflammasome and its impact on tumorigenesis differ across different types of cancer." (PMID 40692785, 2025). "Such efforts will enhance diagnostic precision and accelerate the clinical translation of immunotherapies and targeted therapies centered on NLRP3, ultimately offering more precise and effective treatment strategies for cancer patients." (PMID 40718836, 2025). "NLRP3 is therefore a key mediator of radiation-induced cardiotoxicity, contributing to the worsening of long-term outcomes and quality of life in cancer survivors." (PMID 41272654, 2025).
cancer (continued). "The significant role of the NLRP3 inflammasome in cancer provides new directions for therapeutic strategies." (PMID 40718836, 2025). "Despite the clear critical functions of NLRP3 inflammatory in the immune system, their role in cancer remains quite complex and elusive." (PMID 40671401, 2025). "A database analysis revealed a strong positive correlation between FLT3 and NLRP3 in cancer, which was particularly evident in AML patients." (PMID 39875995, 2025). "The activation of NLRP3 creates chronic inflammation that promotes tumors by inducing DNA damage, enhancing angiogenesis, and suppressing apoptosis in cancer cells." (PMID 41378310, 2025). "A recent study has expanded the conceptual framework of NLRP3 function in cancer beyond its canonical inflammasome activity." (PMID 41291696, 2025). "Summary table of alternative strategies in the regulation of NLRP3 inflammasome via miRNAs and possible molecular outcomes in cancer." (PMID 41560727, 2025). "Concurrently, oxidative stress triggers inflammasome activation, such as the NLRP3 complex, which links ROS directly to chronic inflammation and cancer-promoting pathways." (PMID 41003403, 2025). "Central to this is cytoplasmic multiprotein complex called “NLRP3 inflammasome” which orchestrates innate immune mechanisms to regulate homeostasis or progression to cancer." (PMID 41410801, 2025). "Considering the context-dependent dual effects of the NLRP3 inflammasome in different cancers, further investigation is essential to explore its specific contributions to cancer progression." (PMID 40830103, 2025). "In CRC, aberrant activation of NLRP3 can promote a pro-tumorigenic inflammatory microenvironment that facilitates cancer cell proliferation, invasion, and metastasis." (PMID 40869140, 2025). "While the influence of gut microbiota on cancer is well-established, emerging evidence suggests a reciprocal relationship whereby NLRP3 inflammasome activity significantly shapes the gut microbiome and contributes to tissue homeostasis." (PMID 41376623, 2025). "This review aims to inform the audience about the intricate role of NLRP3 in cancer by summarizing findings across various tissue contexts and cancer hallmarks, focusing on evaluating its potential as a therapeutic target." (PMID 40155968, 2025). "Although clinical investigations of single NLRP3 inhibitors in cancer therapy remain limited, a phase I/ II trial (NCT04971499) is currently underway to evaluate Dapansutrile combination with Pembrolizumab in patients with PD-1-resistant advanced melanoma." (PMID 40830103, 2025). "For validation of the role of NLRP3 in cancer‐related lymphangiogenesis, we conducted HLEC migration assay and HLEC tube formation assay in vitro." (PMID 40135589, 2025). "In this context, the NLRP3 inflammasome is crucial for its divergent role, because it is involved both in cancer progression and regression." (PMID 41560727, 2025). "This dual role highlights NLRP3 as a potential therapeutic target in cancer, as well as its relevance in immune modulation during viral infections like SARS-CoV-2." (PMID 41465546, 2025). "Several studies have also shown the anti-tumorigenic effects of NLRP3 in various cancer types including pancreatic carcinoma and hepatic cancer." (PMID 40692785, 2025). "Summary table of pharmacological inhibitors of NLRP3 inflammasome and their effects in molecular mechanisms in different types of cancer." (PMID 41560727, 2025). "Beyond the general pro-inflammatory effects observed in other inflammasomes, NLRP3 also exhibits inhibitory effects on both inflammation and cancer progression, likely due to its unique “pyroptotic pathway”." (PMID 40718836, 2025). "In contrast, macrophages incubated with CM from untreated cancer cells showed reduced NLRP3 expression and minimal ROS production." (PMID 40002754, 2025).
cancer (continued). "This review aims to synthesize the latest advances on NLRP3 inflammasome biology, its dichotomous involvement in cancer hallmarks, and its specific contributions to OSCC onset, progression, and therapeutic resistance." (PMID 41560727, 2025). "In fact, an increase in the tendency of cancer recurrence and metastasis was observed with increased mRNA expression levels of NLRP3, ASC, IL-1β, and caspase-1." (PMID 41440367, 2025). "In a parallel study, the expression of NLRP3 inflammasome components correlated with the expression of cancer stem cell markers." (PMID 41440367, 2025). "Conversely, the impact of NLRP3 activation in cancer is context-dependent, and both pro-tumorigenic and antitumorigenic effects have been observed." (PMID 39816134, 2025). "The studies reviewed highlight the critical role of regulating autophagy and suppressing inflammatory systems like the NLRP3 inflammasome in managing a wide range of diseases, including cancer, chronic inflammation, and degenerative conditions." (PMID 40671967, 2025). "The NLRP3 inflammasome plays an important role in regulating multiple inflammatory-related diseases, metabolic disorders, autoimmune diseases, and cancer." (PMID 39684769, 2024). "Several phenolic compounds from different natural sources and medicinal plants have been reported to target NLRP3 and exert beneficial effects against NLRP3 inflammasome-related diseases, including cancer." (PMID 39275245, 2024). "In the Nod-like receptor family, pyrin domain containing 3 (NLRP3) inflammasome is one of the critical components of the innate immune system and plays an important role in cancer." (PMID 38392321, 2024). "Therapy with GLP-1 RA reduced ferroptosis and systemic/myocardial levels of NLRP-3, MyD88, IL-1, IL-6 and IL-18, supporting their use in cancer patients treated with anthracyclines and ICIs." (PMID 39457081, 2024). "In our study, aberrant HDAC2 overexpression led to the transcriptional silencing of NLRP3 and suppressed cancer cell pyroptosis." (PMID 38804602, 2024). "This study examines the anti-cancer effects of usenamine A in LUAD and identifies the underlying mechanism involving the activation of NLRP3/caspase-1/GSDMD-mediated pyroptosis." (PMID 38265972, 2024). "NLRP3/caspase-1/GSDMD-mediated pyroptosis is emerging as a promising therapeutic target in cancer treatment, thereby leading to the search for effective drugs and biomarkers for cancer treatment." (PMID 38265972, 2024). "This activation occurs through the secretion of IL-1β, which activates the NLRP3 inflammasome signaling pathway, promoting the inflammatory microenvironment and cancer progression." (PMID 38655063, 2024). "Aberrant expression of PANoptosis-related genes (PRGs), such as NLRP3, caspase-8, and TNFAIP3, has been observed in various cancer types, with remarkable mutations detected." (PMID 38553639, 2024). "In our previous studies, we showed that NLRP3 activation can be used as a treatment tool in cancer cells with low intrinsic NLRP3 activation capacity." (PMID 38543085, 2024). "The intricate relationship between NLRP3 inflammasome activation and cancer progression poses numerous areas for investigation." (PMID 38317229, 2024). "The dual action of the NLRP3 inflammasome in cancer underscores its complex and context-dependent role." (PMID 39769450, 2024). "The NLRP3 inflammasome plays a dual role in cancer, impacting both cancer pathogenesis and therapeutic outcomes." (PMID 39511430, 2024). "Integrated with NLRP3 inflammasome research, targeted pharmacological interventions can alter cell phenotypes promoting cancer, inducing a positive shift towards cell senescence." (PMID 38317229, 2024). "Another important example for the contribution of NLRP3 in the progression of sterile inflammation is in cancer." (PMID 39188718, 2024).